BATF3 (basic leucine zipper ATF-like transcription factor 3)
Diseases named in the same sentence as BATF3 in open-access papers (continued):
Sharing a sentence is not in itself a finding about the gene and the disease.
leishmaniasis (2 papers, 2020 to 2021). Infectious disease that is transmitted through the bite of hematophagous female phlebotomine sand flies. "CD103+ DCs have been shown to be critical for the production of IL-12 in leishmaniasis, and Batf3-/- mice develop an uncontrolled infection over time." (PMID 34699567, 2021). "Thus, the crucial role of Batf3-dependent DCs, differentially imprinting Th responses in the different forms of leishmaniasis, reinforces the possibility of designing vaccines or targeted immunotherapies based on delivery of parasite antigens to this type of DCs." (PMID 33362772, 2020).
leukemia (2 papers, 2021 to 2024). A malignant (clonal) hematologic disorder, involving hematopoietic stem cells and characterized by the presence of primitive or atypical myeloid or lymphoid cells in the bone marrow and the blood. "Numbers and proliferation of TCRTg101 were similar in leukemia-bearing Batf3−/− and Batf3+/+ mice, indicating that cDC1s—the major subset of cross-presenting DCs—were not required for antigen recognition and expansion of TCRTg101in vivo." (PMID 34758311, 2021). "Moreover, in leukemia-bearing Batf3−/− mice largely devoid of cDC1s, TCR2C maintained a naive phenotype and failed to proliferate." (PMID 34758311, 2021).
Obesity (2 papers, 2022). Accumulation of substantial excess body fat. "The authors demonstrate that the abundance of cDC1s in visceral fat tissue is reduced in HFD fed mice and that BATF3-deficiency and the loss of cDC1 results in the development of obesity during ageing." (PMID 35812447, 2022). "Thus, we studied Batf3-deficient mice at 8–9 weeks of life, which is a time point prior to the onset of obesity." (PMID 34983945, 2022). "Next, we determined if BATF3-deficiency also impacts diet-induced obesity." (PMID 35812447, 2022). "Flt3L treatment, which expands the dendritic cell (DC) compartment, mitigated diet-induced obesity and hyperlipidemia in a Batf3-dependent manner." (PMID 34983945, 2022). "Our results shed new light on the role of cDC1s in adipose tissue homeostasis and open new avenues for the treatment of obesity through the potentiation of Batf3-dependent cDC1s." (PMID 34983945, 2022). "Batf3-/- mice have altered IgA-coating of fecal bacteria and displayed microbial dysbiosis marked by decreased obesity protective Akkermansia muciniphila, and Bifidobacterium." (PMID 35812447, 2022). "The earliest metabolic changes that we observed in Batf3-/- mice were increased serum insulin and total cholesterol, which preceded impaired intestinal barrier function, obesity, and changes in lamina propria immune composition." (PMID 35812447, 2022). "Since obesity progresses with an increase in IFN-γ-producing cells in adipose tissue, we hypothesized that Batf3 deficiency may impact DIO." (PMID 34983945, 2022). "We observed an increase in serum total cholesterol, and fasting insulin levels in Batf3-/- mice as early as 8 weeks of age, which preceded the development of obesity, and increased fasting blood glucose levels in Batf3-/- mice compared to WT mice at 16 weeks of age." (PMID 35812447, 2022). "Mechanistically, BATF3-deficiency caused adipose tissue inflammation characterized by an increase in M1-like adipose tissue macrophages and TNFα expression and a decrease of invariant NKT (iNKT) cells that precedes the development of obesity." (PMID 35812447, 2022). "Therefore, we hypothesized that Batf3-dependent cDC1s are critical in triggering obesity." (PMID 34983945, 2022). "To exclude any confounding effects of obesity on its own, we administrated HFD to WT and Batf3-/- mice." (PMID 35812447, 2022).
pancreas tumor (2 papers, 2022 to 2023). "Batf3 is required for tumor-specific T cell priming to a pancreas tumor antigen." (PMID 35393950, 2022).
parasitic infections (2 papers, 2017 to 2020). "Nonetheless, the role of monocytes in these parasitic infections as regulators of Th1 immunity is still contested as other studies identified Batf3 dependent conventional DCs as vital sources of IL-12 to Leishmania65 and to Toxoplasma infection." (PMID 28729715, 2017). "Bioluminescent imaging, as well as in vitro parasite titration, demonstrated that Batf3-deficient mice were unable to control hepatic parasitosis as opposed to wild-type C57BL/6 mice." (PMID 33362772, 2020).
Sepsis (2 papers, 2011 to 2022). Sepsis is defined as life-threatening organ dysfunction caused by a dysregulated host response to infection. "Furthermore, the mregDC module was significantly diminished in Batf3-/- and Irf4-/- septic mice in comparison with wild-type mice with sepsis, reduction in Irf4-/- mice was notably greater." (PMID 35832091, 2022). "These include BATF3, which encodes a leucine zipper protein that functions as a transcriptional repressor, and RETN, which encodes resistin, a serum adipokine that is elevated by sepsis." (PMID 22174891, 2011).
T-Cell Lymphoma (2 papers, 2018 to 2024). "A study from the European T-Cell Lymphoma Study Group identified a set of three genes (TNFRSF8, BATF3, and TMOD1) whose co-expression could potentially distinguish ALK-negative ALCL from PTCL-NOS, with an overall accuracy of approximately 97% in unrelated groups of patients." (PMID 38921179, 2024).
allergic asthma (1 paper, 2023). A asthma with a basis in a pathological type I hypersensitivity reaction. "Whereas the Xcr1+ Irf8+Batf3+ cDC1 showed similar frequencies in all experimental conditions, Xcr1-Irf8+Batf3+ cDC1 frequencies were elevated in the allergic asthma model compared to the allergen tolerance model and controls." (PMID 37251386, 2023). "In order to understand functional differences between Xcr1+Irf8+Batf3+ cDC1 and Xcr1- Irf8+Batf3+ cDC1 clusters, we assessed differential gene expression in allergen-naïve control mice that had not been referred to the allergic asthma model or allergen tolerance model." (PMID 37251386, 2023).
aneurysm (1 paper, 2025). Bulging or ballooning in an area of an artery secondary to arterial wall weakening. "Notably, IRF8 appears to have a more significant role than BATF3, as evidenced by its higher differential expression in human aneurysm tissue microarrays compared to healthy tissue." (PMID 40184622, 2025).
B-cell lymphomas (1 paper, 2018). "Intriguingly, BATF3-expressing B lymphocytes readily induced B-cell lymphomas after characteristic latencies, whereas T-cell transplanted animals remained healthy throughout the observation time." (PMID 29662618, 2018). "Strikingly, BATF3-expressing B cells readily induced B-cell lymphomas in all transplanted mice." (PMID 29662618, 2018). "In conclusion, BATF3 overexpression induces malignant transformation of mature B cells and might serve as a potential target in B-cell lymphoma treatment." (PMID 29662618, 2018). "Indeed, the findings of our Co-IP studies hint at an interaction between BATF3 and JUN, which might be an explanation for the missing BLIMP1 expression in our B-cell lymphomas." (PMID 29662618, 2018).
bladder cancer (1 paper, 2018). "We performed quantitative multiplex immunofluorescence imaging on 64 bladder cancer specimens from patients to investigate the population of immune-infiltrating cells present in the tumor such as BATF3 cells and CD8+ T cells." (PMID 30400835, 2018). "In human bladder cancer specimens, the presence and distribution of tumor- infiltrating BATF3-dendritic cells has not been previously evaluated." (PMID 30400835, 2018).
bone cancer (1 paper, 2021). A primary or metastatic malignant neoplasm affecting the bone or articular cartilage. "To further verify these findings, we used Batf3+/+ and Batf3−/− mice to establish bone cancer pain model." (PMID 34315904, 2021).
brain tumors (1 paper, 2019). "Therefore, the Batf3-dependent CD103+ DC population in the brain is critical for CD8+ T cell-dependent elimination of brain tumors." (PMID 30683885, 2019).
cocaine addiction (1 paper, 2020). "Twelve DEGs (Myct1, Gm21860, Ninj2, Fam183b, Lars2, Alkbh1, Fgf5, Frmd7, Tm6sf2, Wnt6, Batf3, and Clca1) were found to be regulated inversely among the overlap genes, which may be possible targets of RPA to disrupt the cocaine addiction process." (PMID 32489401, 2020).
eosinophilia (1 paper, 2025). "Despite cDC1 deficiency, eosinophilia and neutrophilia in the BAL fluid was not altered in Batf3−/− mice following repeat spore exposure." (PMID 39843887, 2025).
fungal infections (1 paper, 2021). "BATF3-dependent cDC1s are involved in phagocytosis, contributing to protection against some bacterial, viral and fungal infections." (PMID 34723755, 2021).
gastric cancer (1 paper, 2024). A primary or metastatic malignant neoplasm involving the stomach. "Zhangyu Li reported that BATF3 levels were increased in gastric cancer specimens." (PMID 39309860, 2024). "In a study on gastric cancer, the alkaline threonine zipper transcription factor ATF-like 3 (BATF3) was found to act as a key player in cell proliferation." (PMID 39309860, 2024).
Granuloma (1 paper, 2017). A compact, organized collection of mature mononuclear phagocytes, which may be but is not necessarily accompanied by accessory features such as necrosis. "We found that the granulomas developed after the deposition of parasite eggs in the livers of both Batf3−/− and WT control B6 mice." (PMID 28646891, 2017).
hepatocellular carcinoma (1 paper, 2018). A malignant tumor that arises from hepatocytes. "Furthermore, due to overexpression of BATF3 in hepatocellular carcinoma cells, JUN and BATF3 interact at the matrix metalloproteinase-1 (MMP-1) promoter element, resulting in repression of MMP-1 transcription." (PMID 29662618, 2018).
Histiocytosis (1 paper, 2018). An excessive number of histiocytes (tissue macrophages). "Batf3−/− Muhi1 mice started showing signs of histiocytosis between 6 and 8 months of age, with a delay of around 3 months if compared with Mushi1 mice." (PMID 30197645, 2018).
Hypercholesterolemia (1 paper, 2022). An increased concentration of cholesterol in the blood. "BATF3-deficiency leads to early changes in IgA-coating of bacteria, intestinal microbiota composition, hyperinsulinemia, and hypercholesterolemia under normal caloric intake." (PMID 35812447, 2022).
Hyperglycemia (1 paper, 2022). An increased concentration of glucose in the blood. "To assess whether the hyperglycemia that we observed in Batf3-/- mice contributes to the impaired intestinal barrier and subsequent pro-inflammatory phenotype in Batf3-/- mice, we treated 16-week-old WT and Batf3-/- mice with 2-DG, an inhibitor of glucose metabolism, for 10 days." (PMID 35812447, 2022).
Hyperinsulinemia (1 paper, 2022). An increased concentration of insulin in the blood. "Hyperinsulinemia and hypercholesteremia were the first metabolic changes observed in lean Batf3-/- mice and were associated with a decrease of IgAhigh coated fecal bacteria and intestinal dysbiosis." (PMID 35812447, 2022).
Immunodeficiency (1 paper, 2021). Failure of the immune system to protect the body adequately from infection, due to the absence or insufficiency of some component process or substance. "This implies that the ability for Batf3−/− mice to mount a cDC1-dependent immune response is affected by the housing conditions of the animals, where Batf3−/− mice display more severe immunodeficiency when housed in a very clean facility." (PMID 33997687, 2021).
Impaired glucose tolerance (1 paper, 2022). An abnormal resistance to glucose, i.e., a reduction in the ability to maintain glucose levels in the blood stream within normal limits following oral or intravenous administration of glucose. "In contrast, we found increased fasting glucose levels and impaired glucose tolerance in 30-week-old Batf3-deficient mice compared to WT mice." (PMID 34983945, 2022).
liver disease (1 paper, 2025). "Prior work in S. mansoni-liver disease in cDC1-deficient Batf3-/- mice observed a protective role of anti-inflammatory IL-10-expressing CD8 T cells." (PMID 41055564, 2025). "As it was previously reported that Batf3-/- had more severe S. mansoni-induced liver disease but were protected from S. japonicum-liver disease, we assessed the PH phenotype of Batf3-/- mice in S. japonicum-induced PH." (PMID 41055564, 2025).
lung carcinoma (1 paper, 2023). "Venetoclax injections controlled orthotopic TC1 lung cancers in WT bone marrow-reconstituted mice, but completely failed to do so in mice that were reconstituted with bone marrow from Batf3-deficient donors." (PMID 37623817, 2023).
Lymphadenopathy (1 paper, 2018). Enlargement (swelling) of a lymph node. "Additionally, in Batf3−/− Mushi1 mice the progression of the disease was occasionally associated with peripheral lymphadenopathy that instead was never observed in Muhi1 mice." (PMID 30197645, 2018).
lymphoid tumors (1 paper, 2021). "In accordance with these observations, the ability of radiation therapy to induce T cell mediated durable complete remissions of solid and lymphoid tumors was dependent on the presence of CD8+Batf3 dependent DCs, since remissions observed in wild type mice were abrogated in Batf3-/- mice." (PMID 34777358, 2021).
multiple myeloma (1 paper, 2018). "In a multiple myeloma cell line, BATF3 inhibited BLIMP1 expression, potentially illuminating an oncogenic action of BATF3 in B-cell lymphomagenesis." (PMID 29662618, 2018).
neuroendocrine tumors (1 paper, 2022). "The opposite impact of TF score on the survival of NEL and NBL may attributed to BATF3, GMEB1 and REST, since NFIA and ZNF281 showed uniform influence on the survival of the two neuroendocrine tumors." (PMID 36713370, 2022).
ovarian carcinoma (1 paper, 2022). A malignant neoplasm originating from the surface ovarian epithelium. "Indeed, BATF3, IRF5 and ZBTB38 also contributed in evaluation of the response to chemotherapy of breast and ovarian cancer patients." (PMID 35410350, 2022).
psoriasis (1 paper, 2014). An autoimmune condition characterized by red, well-delineated plaques with silvery scales that are usually on the extensor surfaces and scalp. "Namely, RHCG, TCN1, KLK6, and LCN2 were chosen for psoriasis and CCL17, NCF4, BATF3, and CLEC4G as ACD-specific genes." (PMID 25058585, 2014).
pulmonary fibrosis (1 paper, 2025). Chronic progressive interstitial lung disorder characterized by the replacement of the lung tissue by connective tissue, leading to progressive dyspnea, respiratory failure, or right heart failure. "BATF3–/– mice exhibited durable protection from blm-induced pulmonary fibrosis, with less collagen production at 14 days as assessed by hydroxyproline assay and at 21 days as assessed by quantitative real-time PCR (qRT-PCR) for collagen I transcript." (PMID 39964756, 2025).
pulmonary sarcoidosis (1 paper, 2022). Sarcoidosis affecting the lung parenchyma. "We indeed found that essentially all of the IL12B expression was from a similar population of IRF8+XCR1+BATF3+ cDC1s in pulmonary sarcoidosis." (PMID 35668129, 2022).
schistosomiasis (1 paper, 2017). An infectious disease caused by parasitic trematodes of the genus Schistosoma that colonize human blood vessels and release eggs that can cause granulomatous reactions leading to acute (swimmer's itch or acute schistosomiasis syndrome) or chronic disease. "Our study provides evidence that Batf3 is associated with the immunoregulation of the liver granuloma formation, which may confer a new options for schistosomiasis treatment." (PMID 28646891, 2017). "In addition, these novel findings imply that Batf3 may function as a new therapeutic target if it is directly involved in modulating Tc1 cell responses for schistosomiasis and or other immune-associated diseases." (PMID 28646891, 2017).
skin cancer (1 paper, 2023). "Our results show that a marked correlation between the CD103+DC signature (IRF8, FMS‐like tyrosine kinase 3 ligand, CLEC9A, CLNK, XCR1, BATF3, and ZBTB46) and chemokines C‐X‐C motif chemokine ligand 9, CXCL10, and CD8A in a mouse model with DMBA/TPA‐induced skin cancer." (PMID 36891351, 2023).
systemic candidiasis (1 paper, 2025). "In line with this, the model of dermal candidiasis using Batf3-/- mice showed cDC1 dispensability for immunity, whereas cDC1 was important during pulmonary histoplasmosis and systemic candidiasis." (PMID 40491915, 2025).
visceral leishmaniasis (1 paper, 2020). A severe form of leishmaniasis characterized by irregular bouts of fever, substantial weight loss, swelling of the spleen and liver, and anemia (which may be serious). "In this study we sought to determine the role of the basic leucine zipper transcription factor ATF-like 3 (Batf3) in the evolution of infection with Leishmania infantum, the causative agent of human visceral leishmaniasis in the Mediterranean Basin and Latin America." (PMID 33362772, 2020). "To determine the role of Batf3 in visceral leishmaniasis (VL), we have employed C57BL/6 wild-type and Batf3−/− animals challenged with an infective genetically-modified strain expressing red-shifted luciferase (luc) gene." (PMID 33362772, 2020).